CD4 (CD4 molecule)
Diseases named in the same sentence as CD4 in open-access papers (continued):
Sharing a sentence is not in itself a finding about the gene and the disease.
asthma (continued). "Another study has shown that patients with asthma have normal numbers of CD4+CD25hi and CD4+CD25hi FOXP3+ Tregs in peripheral blood compared to healthy individuals, although the expression of the FOXP3 protein was attenuated." (PMID 28589115, 2017). "Methyl-CpG binding domain protein 2 (MBD2) expression increased in CD4+ T cells in peripheral blood samples of asthma patients." (PMID 28808358, 2017). "CD4+ T helper cells play an important role in the pathogenesis of asthma by secreting IL-4, IL-5 and IL-1326." (PMID 28240301, 2017). "IL16 is a T-cell chemo-attractant factor and has been linked to diseases that are characterized by accumulation of CD4+ cells at the site of inflammation, for example, asthma, atopic dermatitis, RA, MS and Crohn's disease." (PMID 28425483, 2017). "In an animal model of asthma using DPP4 (CD26)-deficient rats, it was reported that CD4-positive T-cell migration decreased even with IL-13 stimulation." (PMID 26975422, 2016). "In severe asthma, there were more CD4 cells that expressed IFN-γ, TH17 cells were also more numerous, while both groups had low numbers of TH2 cells." (PMID 27610226, 2016). "CD4+ T cells play a central role in both disease model systems with all the asthma-like features attenuated." (PMID 27255083, 2016). "Allergen provocation outside of pollen season in patients with asthma resulted in a decrease in IL-4+ CD4+ cells." (PMID 27799958, 2016). "We demonstrate here that Itk also plays an important role in the expression of IL-9 and the induction of Th9 cells, a CD4+ T-cell subset relevant to asthma pathology." (PMID 26936133, 2016). "They examined bronchial lavage from severe and mild/moderate asthma, finding that the majority of T cells were CD4." (PMID 27610226, 2016). "The airways of atopic individuals with asthma are characterized by infiltration of mast cells, CD4 T cells and eosinophils, which are activated by exposure to allergens." (PMID 26922672, 2016). "In the clinic elevated numbers of lymphocytes correlate with eosinophilia and asthma severity and this lymphocytosis has been shown to include both CD4+ and CD8+ T cells." (PMID 27112462, 2016). "In the present study we conducted a genome-wide analysis of HDM-driven CD4 T cell responses in sensitized atopics who were stratified on the basis of current asthma symptom expression." (PMID 26922672, 2016). "We confirmed in CD4+ and CD8+ T cells that CTCF binding was almost completely lost in the ZPBP2 intronic region from subjects carrying the asthma-risk SNP, and this finding was true at the allele-specific level." (PMID 27848966, 2016). "The CD4+ T cell is thought to be the dominant active T cell subtype in clinical allergic asthma as well as in animal models of asthma." (PMID 27112462, 2016). "As T cells, especially CD4+ T cells, play a critical role in the pathogenesis of asthma, we focused on AQP3 expression in those cells." (PMID 27165276, 2016). "Together, this clinical study demonstrates the elevation of anti-inflammatory cytokine IL-38 and the decrement of CD4+CD25highFoxP3+ and CD4+CD25highCD127− Treg in childhood asthma." (PMID 27438823, 2016). "Although there are different clinical and cellular phenotypes in asthma, most research in terms of the role of T lymphocytes in this disease has been focused upon CD4+ T cells in the context of chronic airway inflammation." (PMID 28066445, 2016). "TRAP-induced asthma is a distinct phenotype of asthma, which was recently shown by our group to be characterized by increased levels of serum IL-17A in children and increased CD4+IL13+IL17+ double-producing T effector memory cells in mice." (PMID 27777592, 2016). "Yet another insight from the asthma research relates to the distinction between CD4+FoxP3−IL-10+ Tr1 cells and CD4+FoxP3+IL-10− Treg cells." (PMID 25852682, 2015). "Systemic vitamin D status correlated directly with airway levels of IL-10 and CD4+FoxP3+ T cells in pediatric asthma patients and in healthy controls." (PMID 25852682, 2015).
asthma (continued). "Th2 CD4+ T cells are thought to be the central immune cell that regulates allergic airway inflammation in asthma." (PMID 25803300, 2015). "Subsequent studies have highlighted a pathogenic role of CD4+CD161+ T cells in rheumatoid arthritis (RA), juvenile idiopathic arthritis (JIA), Crohn's disease-associated perianal fistulas, and asthma." (PMID 26436101, 2015). "Antigen-activated CD4+ T cells induce several characteristic features of asthma, including the secretion of Th2-type cytokines such as IL-4, IL-5, and IL-13, which are responsible for IgE production by B cells and eosinophil activation and recruitment." (PMID 26385707, 2015). "Th2-type cytokines, including IL-4, IL-5, IL-13, IL-17, and IL-33 produced by activated CD4+ T-cells, enhance IgE production, eosinophil accumulation, and play a central role in the pathogenesis of asthma." (PMID 26385707, 2015). "The experimental asthma mice had higher CD4+IL-17A+ cell numbers and decreased CD4+Foxp3+ cell numbers in BALF as compared to NC mice (p < 0.01)." (PMID 26612993, 2015). "Because asthma is believed to be a CD4+ T cell–mediated disease, we used CD8-depleted PBMC cultures with T-cell stimulation, as performed in our previous studies, to compare T-cell immunophenotypes in both patients with SS and those with SR asthma." (PMID 25772594, 2015). "In a study of CD4+T lymphocytes of patients with asthma, stimulated with allergens, there was a significant correlation between the degree of methylation and IL-4 concentration." (PMID 25859290, 2015). "CD4+ T cells are generally essential for allergen-induced airway inflammation, and asthma is considered as a dysregulated Th2 response." (PMID 25803300, 2015). "In the development of asthma, allergen-specific CD4+ T cells play a pivotal role by facilitating airway inflammation, which is largely mediated by type 2 T-helper (Th2) cytokines such as interleukin 4 (IL-4), IL-5 and IL-13." (PMID 26488300, 2015). "Similar change was found in the present study; that is, the proportion of Th17 cells in isolated spleen CD4+ T cells was significantly increased in OVA-induced asthma mice compared to the sham group." (PMID 26339131, 2015). "Asthma historically was characterized as being a CD4+ TH2-mediated disease with increased production of IL-4, IL-13, and IL-5." (PMID 25772594, 2015). "Functional defects in IL-10-producing CD4+ Tr1 cells have also been described in asthma and rheumatoid arthritis." (PMID 25852682, 2015). "IL-5 regulates the development, activation, migration, and survival of eosinophils and stimulates the expression of IL-6, which is a T- and B-cell growth factor that produces IgE and regulates CD4+ T-cell function to induce asthma." (PMID 25658604, 2015). "Our study also identified, for the first time, reduced numbers of CD3+CD4+FOXP3+ Treg cells in patients with severe asthma." (PMID 25746968, 2015). "IL-4 directly promotes the polarization of naïve CD4+ T cell differentiation towards Th2 phenotype, which initiates inflammatory responses and propagates the symptoms of asthma." (PMID 26488300, 2015). "Asthma is characterized by the presence of eosinophils, mast cells, and CD4+ T lymphocytes; whereas COPD is distinguished by the dominance of neutrophils, macrophages and CD8+ T lymphocytes in the respiratory tract." (PMID 26617525, 2015). "In vivo, they inhibit inflammation in a murine model of asthma, in particular the recruitment of eosinophils, dendritic cells and CD4+T cells." (PMID 26442456, 2015). "When CD4+ T cells from asthma patients were stimulated with dust mite allergen in the presence of calcitriol, the hormone decreased IL-5, IL-9, and IL-13 production." (PMID 25852682, 2015). "Both proportion and cell counts of CD4+IL-17A+ cells increased and CD4+Foxp3+ cells decreased in asthma model." (PMID 26612993, 2015).
asthma (continued). "Quantitative and functional impairment of pulmonary CD4+CD25+Foxp+ Treg cells in pediatric asthma patients has been observed, demonstrating that CD4+CD25+FOXP3+ Treg cells can reverse established allergic airway inflammation and prevent airway remodeling." (PMID 26565810, 2015). "Administration of L. johnsonii (La-1) to mice with branchial induced asthma dampened the autoimmune response by reducing the proportion of CD4+ T lymphocytes expressing IL-4 and increasing CD4+ T lymphocytes expressing IFNγ." (PMID 26275147, 2015). "For example, cg13512987, located in the first exon of the cluster of differentiation 4 (CD4) gene, was significantly hypermethylated in asthma-affected twins compared to their unaffected co-twin." (PMID 26691723, 2015). "Dysregulated T helper type 2 (Th2)-biased immune responses directed against antigens and impaired CD4+CD25+ forkhead box P3 (FoxP3)+ Treg cells play important roles in the development of asthma." (PMID 25177863, 2014). "And in the previous study, by inhibiting Notch signal in spleen CD4+T cells of allergic asthma mice, we have demonstrated in vitro that Notch signal plays an important role in asthma." (PMID 24706026, 2014). "In mucosal sites, aberrant immune function and cross-reactivity of CD4 TRM in peripheral tissues are being investigated in inflammatory bowel disease (IBD) and asthma as possible causes of chronic or remitting immunopathology." (PMID 25071787, 2014). "Vitamin D is able to modulate the function of CD4+ T cells particularly reversing the defective induction of IL-10-secreting regulatory T cells in glucocorticoid-resistant asthma patients." (PMID 25061262, 2014). "Many inflammatory cells such as T lymphocytes, eosinophils and mast cells play a defensive role in the pathogenesis of asthma, in which the most important element is the activation of CD4+T cells." (PMID 24706026, 2014). "Asthma is a chronic inflammatory lung disease stimulated by aberrant allergen-specific CD4+ T helper-2 (TH2) secreting cytokines, IL-2, -4, -5, -9, and -13 in response to various stimuli, such as allergens, infections, and air pollutants." (PMID 24991086, 2014). "In this study we analyzed the incidence of different subsets of CD4+ T cells together with the co-expression of various cytokines in BAL fluid of asthma patients and healthy subjects." (PMID 25132806, 2014). "T lymphocytes, in particular CD4+ T cells, function as orchestrators of the inflammatory response and play an important role in the pathogenesis of asthma." (PMID 25019045, 2014). "Unexpectedly, significant decreases in subepithelial CD4+ counts from baseline were seen at week 6 in both normal subjects (P = .016) and subjects with asthma (P = .013)." (PMID 24457412, 2014). "YPFS affected TCR and MHC class II expression on CD4+ T cells in a mouse model of asthma, and regulated the balance of Th1/Th2 cells in murine allergic airway disease." (PMID 25198676, 2014). "The percentage of CD4+CD25high cells was decreased in bronchoalveolar lavage (BAL) fluid of pediatric asthma patients." (PMID 25132806, 2014). "At day 4, epithelial CD4+ counts in subjects with asthma correlated with total chest symptom scores recorded during the 2-week postinfection period (r = 0.69, P = .029)." (PMID 24457412, 2014). "CD4+ T cells are one of the most important cells in the pathogenesis of airway inflammation in asthma." (PMID 25132806, 2014). "The major feature of asthma is an airway inflammation, in which CD4 T-lymphocytes, eosinophils and mast cells are predominantly involved." (PMID 25264130, 2014). "Our study is the first to show the decreased population of CD4+Foxp3+TGF-β+ cells in BAL fluid of asthma patients." (PMID 25132806, 2014). "The results indicated that the number of IL-17+ CD4+ T cells (Th17) in the lung tissue was significantly increased in asthma group mice compared with control group mice (P < 0.01)." (PMID 24959003, 2014).
asthma (continued). "A significantly higher percentage of CD4+Foxp3+ cells from asthma patients expressed IFN-γ (P = 0.01), IL-4 (P = 0.004) and CD25 (P = 0.04), whereas the percentage of CD4+IL-10+ cells expressing Foxp3 was significantly decreased in asthmatics (P = 0.03)." (PMID 25132806, 2014). "Compared with normal subjects, subjects with asthma had a significantly greater number of subepithelial CD4+ cells at baseline (P = .043)." (PMID 24457412, 2014). "As DNA methylation in different tissue types can vary and appropriate biomarkers for epigenetic asthma research are needed, we sought to determine the relationship between CD4+ lymphocyte and buccal cell IFNγ promoter methylation in allergic asthmatics." (PMID 24891923, 2014). "In asthma, the CD4+ T cells, a type of lymphocyte, are the crucial mediators of a Th2 type immune response in the bronchial airway, whereas the CD8+ T cells are more important in COPD." (PMID 25528348, 2014). "Previously, we have already shown that the mainly cells present in airway walls of this asthma model are eosinophils, CD4+ lymphocytes, iNOS and nNOS positive cells." (PMID 23947680, 2013). "In contrast, it has been reported that the majority of IL-22-producing CD4+ T cell lines which are generated from lung biopsy specimens of asthma patients produce IFN-γ." (PMID 23577040, 2013). "Clinically, asthma patients are reported to have elevated numbers of CD4+ T (Th2 subtype) cells in the airways." (PMID 23388501, 2013). "The majority of IL-22-producing cells in peripheral blood of asthma patients are CD4+CCR6+CD161+ cells, suggesting that Th17 cells are the main producer of IL-22." (PMID 23577040, 2013). "The Treg cells/CD4+ Tcells were significantly increased in the asthma attack group (%) compared to the control groups (5%), and were prominently reduced upon Budesonide treatment (, p<0.05%)." (PMID 23717481, 2013). "A recent study has shown that weight reduction with intervention such as bariatric surgery can significantly improve asthma control and treatment responses in asthma, but increase CD4 lymphocytes and their cytokine secreting potential." (PMID 23970905, 2013). "Because they orchestrate the Th2 response that characterizes asthma, including the production of type 2 cytokines, mucus hypersecretion, and IgE over-production, activation of CD4+ T cells by APCs is a key step in the progression of asthma symptoms." (PMID 23326313, 2013). "We also observed an increase of CD4+IL-17+ T cells in acute asthma, reinforcing the importance of IL-17A in the immunopathology of asthma." (PMID 23822853, 2013). "We found that the percentage of CD4+ T cells was higher in all groups (mild P = .007, moderate P = .0001, acute P = .04) the highest being in moderate asthma patients (P = .03)." (PMID 23822853, 2013). "Bronchial asthma patients display hypermethylation of the IFNG gene in CD4+ T cells following allergen challenge which correlated with decreased IFNG expression." (PMID 24244422, 2013). "The cytokine IL-6 regulates the functions of CD4 T cells and mediates asthma induction, whereas IL-12 regulates the Th1/Th2 balance and promotes IFN-γ production." (PMID 23451048, 2013). "Since CD4+ T cells play a pivotal role in asthma, in this study we focused on the development of CD4+ T subsets with age following maternal PM exposure." (PMID 23856009, 2013). "Bronchoalveolar lavage fluid (BALF) from asthma patients contains high amounts of IL-4/IL-17A double-positive CD4+ T cells, and moderate-to-severe human asthma patients have more IL-17A-positive cells in bronchial submucosa than mild asthma patients." (PMID 23383714, 2013). "Overexpressing the IL-18 protein in the lungs induces type 1 and type 2 cytokines and airway inflammation, and results in increasing airway hyperresponsiveness via CD4+ T cells and IL-13 in asthma." (PMID 23382928, 2013).
asthma (continued). "Although distinct subsets of iNKT cells have been reported to be involved in different forms of asthma, they are now consolidated into CD4− and/or CD4+ IL-17RB+iNKT cell subsets." (PMID 22346732, 2012). "Significant reduction of the CD4+CD25+ Treg cell frequency in peripheral blood was detected in patients with persistent or exacerbation of asthma when compared to control groups." (PMID 22792275, 2012). "The ratio of NKT cells and CD4+NKT cells in SIT group was higher than that in asthma group (P < 0.05), but still lower than that in the normal control group (P < 0.01)." (PMID 23008731, 2012). "In summary, this study indicated that there was a reduction in number of peripheral blood NKT cells and CD4+NKT cells in patients with asthma, as well as change of cell function." (PMID 23008731, 2012). "The literature overwhelmingly confirms that CD4+ T cells play an important role in the occurrence and development of asthma, and an increasing amount of evidence supports the concept that these cells also influence susceptibility to depression." (PMID 23110234, 2012). "Compared with normal control group, the rate of NKT and CD4+NKT cells significantly decreased in children with asthma (P < 0.01)." (PMID 23008731, 2012). "CD4+ CD25+ T regulatory cells have also been shown to significantly reduce AHR in mouse models of asthma 49–51." (PMID 22093101, 2012). "It has been shown that CD4+ Th2 cells play a pivotal role in the pathogenesis of asthma and other allergic inflammatory diseases." (PMID 22514638, 2012). "It has been generally accepted that disturbance of Th1 and Th2 plays an important role in the pathogenesis of asthma, highlighting the importance of T-helper cell (CD4+) activation and differentiation in asthma." (PMID 23071776, 2012). "This is the first study to correlate genome-wide CD4+ T cell transcript abundance with IgE level in humans and is, to our knowledge, the largest gene-expression study of as asthma-related quantitative phenotype published to date." (PMID 21473777, 2011). "We also observed an increase in CFL1, which has been implicated as an inhibitor of glucocorticoid function in hormone-resistant HeLa cells and in CD4+ T cells from patients with severe, glucocorticoid-insensitive asthma." (PMID 21388553, 2011). "Peripheral blood CD4+ T cells from 223 participants from the Childhood Asthma Management Program (CAMP) with simultaneous measurement of IgE." (PMID 21473777, 2011). "The adoptive transfer of only ELP+ CD4+ T lymphocytes reinstating the asthma phenotype indicates conclusively that it was the afferent arm of the Th2 immune response that was affected." (PMID 21835035, 2011). "Surprisingly, we found that these ELP-/- did respond to the OVA challenge and developed a significant asthma phenotype (Gr#2) compared to either the Grs# 3 or 4 where CD4+ T cells from spleen of sensitized ELP-/- mice were used." (PMID 21835035, 2011). "Another study found that circulating FOXP3+/CD4+ ratio was significantly low in patients with asthma and atopic dermatitis." (PMID 22164170, 2011). "CD4+ T cell microlocalization within ASM layer was first reported in an elegant experimental rat asthma model." (PMID 22220184, 2011). "Using flow cytometric assay of the whole blood from children with asthma, we demonstrated significantly higher frequencies of both CD4+ and CD8+T cells expressing IL-4 and IL-13 compared with blood obtained from healthy, nonatopic children." (PMID 21197090, 2010). "Most A. fumigatus proteins that serve as allergens have been identified from screens identifying proteins that bind IgE antibody or, less commonly, stimulate CD4+TH2 clones in people with asthma or ABPA." (PMID 20174463, 2010). "In contrast, an increase in IL-13 in CD4+ T cells in severe asthma was revealed, though it was only significant as compared to intermittent asthma." (PMID 21197090, 2010).